SLC16A1 (solute carrier family 16 member 1)
Description:
Bidirectional proton-coupled monocarboxylate transporter. Catalyzes the rapid transport across the plasma membrane of many monocarboxylates such as lactate, pyruvate, acetate and the ketone bodies acetoacetate and beta-hydroxybutyrate, and thus contributes to the maintenance of intracellular pH. The transport direction is determined by the proton motive force and the concentration gradient of the substrate monocarboxylate. MCT1 is a major lactate exporter (By similarity). Plays a role in cellular responses to a high-fat diet by modulating the cellular levels of lactate and pyruvate that contribute to the regulation of central metabolic pathways and insulin secretion, with concomitant effects on plasma insulin levels and blood glucose homeostasis (By similarity). Facilitates the protonated monocarboxylate form of succinate export, that its transient protonation upon muscle cell acidification in exercising muscle and ischemic heart. Functions via alternate outward- and inward-open conformation states. Protonation and deprotonation of 309-Asp is essential for the conformational transition.
Synonyms: MCT1; MCT; HHF7; MCT1D
Tractability: Small molecule: a structure with a bound ligand is known; a high-quality ligand is known; it belongs to a druggable protein family. Antibody: UniProt places it where antibodies can reach, with high confidence; its Gene Ontology location is reachable by antibodies, with high confidence; UniProt predicts a signal peptide or a membrane-spanning region; the Human Protein Atlas places it where antibodies can reach. PROTAC: ubiquitination databases record sites on it; its protein half-life has been measured; a small molecule that binds it is known.
Target class: SLC16 family of monocarboxylate transporters; Electrochemical transporter; SLC superfamily of solute carriers; Transporter
Chemical probes: AR-C141990 (high quality), AR-C155858, AZD3965 (high quality), PD082632, PD083498, SR 13800 (high quality)
Gene: Protein-coding gene on chromosome 1 (112,911,847 to 112,957,593, reverse strand). Ensembl gene ENSG00000155380.
Subcellular location: Cell membrane; Basolateral cell membrane; Apical cell membrane
Subcellular location (Human Protein Atlas): Cell Junctions; Plasma membrane
Pathways (Reactome):
Disease: Defective SLC16A1 causes symptomatic deficiency in lactate transport (SDLT)
Drug ADME: Aspirin ADME
Hemostasis: Basigin interactions
Transport of small molecules: Proton-coupled monocarboxylate transport
Gene Ontology:
Molecular function: lactate:proton symporter activity; monocarboxylic acid transmembrane transporter activity; protein binding; succinate transmembrane transporter activity; succinate:proton symporter activity; carboxylic acid transmembrane transporter activity; lactate transmembrane transporter activity; mevalonate transmembrane transporter activity; identical protein binding; secondary active monocarboxylate transmembrane transporter activity; solute:proton symporter activity; transmembrane transporter activity
Biological process: centrosome cycle; monocarboxylic acid transport; succinate transmembrane transport; carboxylic acid transmembrane transport; mevalonate transport; plasma membrane lactate transport; transport across blood-brain barrier; behavioral response to nutrient; glucose homeostasis; lactate transmembrane transport; lipid metabolic process; proton transmembrane transport; pyruvate catabolic process; pyruvate transmembrane transport; regulation of insulin secretion; response to food; transmembrane transport
Cellular component: apical plasma membrane; basal plasma membrane; cell junction; centrosome; extracellular exosome; lateral plasma membrane; membrane; plasma membrane; basolateral plasma membrane; synapse
Genetic constraint (gnomAD): Loss-of-function variants: 12 observed, 32.9 expected, observed/expected ratio (o/e) 0.36, 90% interval 0.23 to 0.59. The upper end of that interval is the gene's LOEUF score, 0.59, which puts it in group 2 of 6, group 1 being the genes least tolerant of losing a copy. Missense variants: 425 observed, 629.97 expected, observed/expected ratio (o/e) 0.67, 90% interval 0.62 to 0.73. Synonymous variants: 227 observed, 234 expected, observed/expected ratio (o/e) 0.97, 90% interval 0.87 to 1.08.
Homologues: Orthologues: chimpanzee SLC16A1 (99% identical), macaque SLC16A1 (97% identical), rabbit SLC16A1 (87% identical), mouse Slc16a1 (86% identical), guinea pig SLC16A1 (85% identical), rat Slc16a1 (85% identical), dog SLC16A1 (77% identical), tropical clawed frog slc16a1 (73% identical), zebrafish slc16a1b (71% identical), zebrafish slc16a1a (68% identical), Caenorhabditis elegans mct-6 (28% identical), Drosophila melanogaster CG13907 (28% identical), and 11 more. Paralogues in human: SLC16A7 (57% identical), SLC16A3 (41% identical), SLC16A8 (37% identical), SLC16A6 (29% identical), SLC16A12 (27% identical), SLC16A5 (27% identical), SLC16A13 (26% identical), SLC16A11 (26% identical), SLC16A14 (25% identical), SLC16A10 (22% identical), SLC16A9 (22% identical), SLC16A4 (22% identical), and 1 more.
Diseases named in the same sentence as SLC16A1 in open-access papers:
SLC16A1 is named in the same sentence as 110 diseases in open-access papers, as found by Europe PMC text mining. Sharing a sentence is not in itself a finding about the gene and the disease. The quoted sentences say what the papers report.
breast carcinoma (19 papers, 2014 to 2025). "For instance, MCT1 (SLC16A1), a predicted direct target of miR-342-3p, acts as a monocarboxylate transporter which serves as the main lactate transporter in breast cancer cells and its over-expression has been associated with poor clinical outcomes." (PMID 30115973, 2018). "Conversely, in both breast cancer cell lines, O-desmethyltramadol consistently downregulated the expression of SLC16A1, CD22, NUPR1, ASNS, and DDIT3." (PMID 40362379, 2025). "In contrast, SLC16A3 mRNA expression was high and SLC16A1 mRNA expression very low in luminal B breast cancer tissue." (PMID 34219652, 2021). "Although we know that breast cancer is also a highly glycolytic malignant tumor, our bioinformatics prediction of SLC16A1 still requires more experimental studies for validation." (PMID 32355273, 2020). "Furthermore, past research has demonstrated SLC16A1's significant role in drug resistance in colon cancer and breast cancer 28, 29, indicating its potential involvement in tumor drug resistance." (PMID 38911368, 2024). "Hypoxia inducible factor 1 subunit alpha (HIF1A) and the lactate transporter solute carrier family 16 member 1(SLC16A1) also regulate aerobic glycolysis in cancer metabolism, whose high expressions are correlated with poor clinical outcomes in breast cancer patients." (PMID 37180167, 2023). "SLC16A1 mRNA, encoding MCT1, and SLC16A3 mRNA, encoding MCT4, both showed high expression levels in basal-like breast cancer characterized by high proliferative and glycolytic activity." (PMID 34219652, 2021). "Moreover, our research has a limitation in that the bioinformatics analysis for SLC16A1 was based on the RNA-seq data from the knockdown of SLC16A1 in human breast cancer, which weakened the biological process predictions of pancreatic cancer." (PMID 32355273, 2020). "However, LEC gene expression data of MCF-7 cc and SK-BR-3 cc suggested import and export of lactate between breast cancer cells and LECs could occur at similar rates since SLC16A1 and SLC16A3 expression were similar." (PMID 33277521, 2020).
hyperinsulinism (14 papers, 2012 to 2025). Abnormally high levels of insulin in the blood. "The aberrant activation of LDHA or SLC16A1 has been observed to cause diabetes-like phenotype or exercise-induced hyperinsulinism (EIHI)." (PMID 35569803, 2023). "If endogenous hyperinsulinism is diagnosed, an investigation for SLC16A1 (coding for monocarboxylate transporter 1) mutation should be done." (PMID 22587661, 2012). "Overexpression of SLC16A1 has in mouse pancreatic β cells been found to induce hyperinsulinism during exercise." (PMID 34620218, 2021). "Overexpression of monocarboxylate transporter-1 (Slc16a1) in mouse pancreatic β-cells leads to relative hyperinsulinism during exercise." (PMID 28443133, 2017). "Failure of repression of MCT1 was observed in a rare genetic disease called exercise-induced hyperinsulinism and the same phenotype was described in transgenic mice with forced expression of Slc16a1 in beta cells." (PMID 28792951, 2017). "Constructing Slc16a1 knockout mouse model demonstrated that SLC16A1 may contribute to the treatment of exercise-induced hyperinsulinemia, at the same time, it may exacerbate ketoacidosis." (PMID 39850557, 2024). "Among the reported Turkish patients, there was no case with exercise-induced hyperinsulinism (SLC16A1), glucokinase-induced hyperinsulinism, or mutations in the UCP2, HNF4A, and HNF1A genes, while one patient had GLUD1 gene mutation." (PMID 27181376, 2016). "Moreover, forced overexpression of Slc16a1 in β cells leads to insulin secretion in response to muscle-derived pyruvate and is thought to be responsible for exercise-induced hyperinsulinism in humans." (PMID 25497096, 2014). "Mutations in eight different genes (ABCC8, KCNJ11, GLUD1, CGK, HADH, SLC16A1, HNF4A and UCP2) have been identified to date in patients with congenital forms of hyperinsulinism (CHI)." (PMID 23032149, 2012).
pancreatic cancer (13 papers, 2015 to 2025). "Our results suggest that crosstalk via direct cell-to-cell transfer of cellular components foster chemotherapy-induced tumor evolution and that targeting of CD44 and MCT1(encoded by SLC16A1) may be useful strategy to prevent recurrence of gemcitabine-exposed pancreatic cancers." (PMID 36302783, 2022). "SLC16A1 was undetectable in 2 normal pancreatic samples, but expressed in 11 out of 12 pancreatic cancer patients (6 with moderate-high expression, 1 with high expression)." (PMID 41346619, 2025). "Next, we investigated the combined effect of CD24, CD44, and SLC16A1 expression on the prognosis of the pancreatic cancer patients." (PMID 36302783, 2022). "In detail, in pancreatic cancer, the SLC16A1 and SLC16A4 mRNA expression levels increased in all 3 cases." (PMID 32355273, 2020). "In pancreatic cancer samples, there were distinguishable patterns for SLC16A1, as only strong staining was positive on the cell membrane." (PMID 32355273, 2020). "The boxplot of the RNA-Seq expression in 179 pancreatic cancer vs 171 normal pancreas samples demonstrated that SLC16A1, SLC16A2, SLC16A3, SLC16A4, SLC16A5 and SLC16A13 were increased with statistical meaning." (PMID 32355273, 2020). "The relative staining intensity for SLC16A1 was weak (2 cases) for normal tissue and weak (2 cases), moderate (5 cases) and strong (5 cases) for pancreatic cancer cases." (PMID 32355273, 2020). "Moreover, a high expression level of CD44 and/or SLC16A1 was correlated with a relatively unfavorable survival in pancreatic cancer patients." (PMID 36302783, 2022). "However, more research attention should be paid to the association between SLC16A1, SLC16A3 and pancreatic cancer as new indicators in large patient cohorts." (PMID 32355273, 2020). "The median expression level for SLC16A1 could be considered a significant prognosis marker for overall survival time for pancreatic cancer with an HR value = 1.6 and log rank P-value = 0.032." (PMID 32355273, 2020). "Moreover, miR124 known to regulate multiple proliferation-related genes in pancreatic cancer cells such as cyclin-dependent kinase 6, Cyclin A2, forkhead box A2 and solute carrier family 16, member 1 (SLC16A1)." (PMID 27240340, 2016). "However, in our selected validation cohort (GSE28735), which contains 45 pancreatic cancer patients with overall survival time, we observed that SLC16A1 and SLC16A3 only demonstrate the same trend if separated the patients into high and low groups at median expression." (PMID 32355273, 2020). "Alternatively, SLC16A1 and MYOF showed a trend toward increased expression in pancreatic cancer tissues." (PMID 39897130, 2025). "The studies from the Oncomine database also clearly show the differences in increasing levels of SLC16A1 and SLC16A3 between pancreatic cancer and normal tissue." (PMID 32355273, 2020). "One gene, SLC2A1, is present in five tumor entities (renal, urothelial, lung, liver and pancreatic cancer) and PLS3, SLC16a1, and SLC16A3 are present in four tumor entities." (PMID 32599841, 2020). "Taken together, our findings, including the IHC pattern, demonstrated that SLC16A1 and SLC16A3 could be potentially ideal prognosis makers and therapy targets for patients with pancreatic cancer as treatment strategies." (PMID 32355273, 2020). "These significantly enriched GO terms and KEGG pathways could help us deeply understand the function of SLC16A1 and SLC16A3, which are involved in the occurrence and progression of pancreatic cancer." (PMID 32355273, 2020). "SLC16A1, SLC16A3 and SLC16A13 exhibited biomarker potential for prognosis, and we further identified their related genes and regulatory networks, revealing core molecular pathways that require further investigation for pancreatic cancer." (PMID 32355273, 2020).
glioma (12 papers, 2019 to 2025). A benign or malignant brain and spinal cord tumor that arises from glial cells (astrocytes, oligodendrocytes, ependymal cells). "In this study, by downloading glioma-related datasets from TCGA, CGGA, and GEO, we analyzed the expression, prognosis, and diagnostic values of LDHA and SLC16A1 in LGG cohorts." (PMID 40782248, 2025). "The protein levels of LDHA and SLC16A1 were analyzed using the Human Protein Atlas (HPA) database, and the differential expression and function of LDHA and SLC16A1 were validated in glioma cell lines." (PMID 40782248, 2025). "The immunohistochemical images of LDHA and SLC16A1 in normal cerebral cortical and glioma tissues were retrieved from the HPA database." (PMID 40782248, 2025). "SLC16A1 expression was shown to be increased in high-grade gliomas compared with healthy controls and low-grade gliomas." (PMID 37298344, 2023). "When grouping these glioma subtypes together, those with high expression of SLC16A1 led to significantly lower survival compared to those with low expression of SLC16A1." (PMID 34685601, 2021). "SLC16A1 has a significantly increased expression level in brain and CNS cancer, esophageal cancer, head and neck cancer, kidney cancer, lung cancer, melanoma, and even sarcoma, indicating its importance in pan-cancer." (PMID 32355273, 2020). "Hypoxia also induced increased SLC16A1 plasma membrane expression in glioma cells, both in in vitro and in vivo models." (PMID 31414377, 2019). "Additionally, low SLC16A1 expression inhibited the proliferation, migration, and invasion of glioma cells." (PMID 40782248, 2025). "Overexpression of SLC16A1 also predicted poor survival of high-grade gliomas." (PMID 36203434, 2022). "To evaluate the levels of lactate metabolism in glioma, we analyzed the mRNA levels of LDHA and MCT1 (referred as SLC16A1 at the mRNA level) using bulk RNA-seq data from the TCGA and CGGA datasets." (PMID 38576043, 2024). "Together, our results and previous findings indicate that, among the PRLMGs, SLC16A1 and TET2 are potentially important targets for intervention of glioma lactate metabolism that deserve priority in future investigation." (PMID 36203434, 2022). "The results showed that glioma tissues have higher expression of LDHA, HLF1A, SLC16A1, and MRS2 and lower expression of LDHB and SLC25A12 compared with paracancerous tissues." (PMID 36698888, 2022). "SLC16A1 overexpression and downregulation of LDHA have been validated in glioma cell lines." (PMID 40782248, 2025). "SLC16A1 expression is significantly higher in high-grade gliomas than in non-tumor controls and low-grade gliomas, and patients with high SLC16A1 expression have a poor prognosis." (PMID 36894874, 2023). "Our study showed that LDHA, MRS2, and SLC16A1 were indicators of poor survival, while LDHB and SLC25A12 were indicators of favorable prognosis, suggesting that lactate metabolism is dysregulated in glioma and this dysregulated expression is closely related to tumor progression." (PMID 36698888, 2022). "The expression levels of EMB, LDHA, SLC16A1, SLC16A3, SLC16A8, PARK7, and PFKFB2 were lower in 1p/19q Codel glioma than those in non-Codel glioma." (PMID 36698888, 2022). "A recent study revealed that the mRNA level of SLC16A1 was significantly increased in high-grade gliomas compared to LGG and non-tumor controls, suggesting that SLC16A1 expression is positively correlated with WHO pathological grading and poor survival of gliomas." (PMID 40782248, 2025).
glioblastoma (10 papers, 2018 to 2025). The most malignant astrocytic tumor (WHO grade IV). "Furthermore, the monocarboxylate transporters 1 and 4 (MCT1 and MCT4, encoded by SLC16A1 and SLC16A3, respectively) that are typically overexpressed in glioblastomas, are underexpressed or silenced in glioblastomas that possess IDH1 mutations." (PMID 33019704, 2020). "Genetic abnormalities in SLC16A1 have been identified to cause congenital hyperinsulinism; PCDH9 is a non-clustered protocadherin, mutations in humans are associated with autism spectrum disorders and its expression in glioblastoma suggest a role as tumor suppressor." (PMID 30166318, 2018).
Hypoglycemia (10 papers, 2008 to 2024). A decreased concentration of glucose in the blood. "Anaerobic exercise can induce hypoglycemia in some patients with activating variants in the promoter region of SLC16A1, the gene encoding the monocarboxylate transporter 1 (MCT1) pyruvate transporter reported in a small number of cases." (PMID 37454648, 2024). "Patients with heterozygous or homozygous inhibiting mutations in SLC16A1 present with moderate or profound ketosis and sometimes hypoglycemia during fasting or infections, within the first years of life." (PMID 35422763, 2022). "Patients with heterozygous or homozygous inhibiting mutations in SLC16A1 presented with moderate or profound ketosis and sometimes hypoglycemia at fasting or during infections, with onset in the first years of life." (PMID 33849624, 2021). "A hypoglycemia panel eventually revealed a pathogenic mutation in the gene SLC16A1 (also called MCT-1), encoding monocarboxylate transporter 1, which is critical for ketone utilization and has been found to be a rare cause of KH." (PMID 31700521, 2019). "Inactivating recessive homozygous or heterozygous mutations in the SLC16A1 gene were described in patients with recurrent ketoacidosis and hypoglycemia, a potentially lethal condition." (PMID 31380330, 2019). "Mutations in the SLC16A1 gene that result in its aberrant expression in β-cells provoke exercise-induced hypoglycemia by enabling pyruvate-induced insulin secretion." (PMID 25982967, 2015). "Whereas hypoglycaemia in SLC16A1 mutation carriers is exercise-induced and it is the anaerobic type of exercise that these patients need to eliminate in order to minimize the number of hypoglycaemic episodes." (PMID 26316429, 2015). "Exercise-induced hypoglycaemia, also caused by hyperinsulinaemia, has been described both in childhood and adulthood and is due to failed silencing of monocarboxylate transporter 1 in pancreatic β cells, which is coded by the SLC16A1 gene." (PMID 22587661, 2012). "However, in the presence of 2.5 mM glucose, which better mimicks the hypoglycemia which occurs during fasting in vivo, 5 to 20 mM of BHB did not change the gene expression of Slc16a1 (closed bars)." (PMID 38589879, 2024).
melanoma (9 papers, 2020 to 2025). A malignant, usually aggressive tumor composed of atypical, neoplastic melanocytes. "SLC16A1, a member of the SLC transporter superfamily, is highly expressed in melanoma." (PMID 36143291, 2022). "The transport of lactate by SLC16A1 into the TME leads to increased cellular metabolism and promotes the survival of melanoma cells and could represent a potential prognostic biomarker." (PMID 36143291, 2022).